BCL2 (BCL2 apoptosis regulator)
Diseases named in the same sentence as BCL2 in open-access papers (continued):
Sharing a sentence is not in itself a finding about the gene and the disease.
tumor (continued). "It was found that 9.2% of the tumours were completely negative, 17.2% weakly (1 + 2), 41.6% moderately (3 + 4) and 31.9% strongly positive (5 + 6) for Bcl-2." (PMID 8679463, 1996). "The aim of this study was to assess relationships between Bcl-2 expression, response to chemotherapy and a number of pathological and biological tumour parameters in premenopausal, lymph node-negative breast cancer patients." (PMID 8679463, 1996). "Tumour cell staining with the bcl-2 antibody was significantly reduced when tumour mass had to be left behind compared with those with no visible remaining tumour (P = 0.03 and 0.003 for weakly and strongly stained tumours respectively)." (PMID 7577491, 1995). "The relation between bcl-2 protein expression and survival was small, depending on the primary localisation of the tumour (in lymph node of mucosae), and lacked a significant correlation with overall survival." (PMID 8297731, 1994). "A strong negative relationship was observed, with 26 of 88 (30%) bcl-2-positive tumours being EGFR positive, compared with 16 of 23 (70%) bcl-2-negative tumours being EGFR positive (P = 0.001), raising the possibility that bcl-2 is an ER-regulated gene." (PMID 8286195, 1994). "Indeed, in our cell lines of DLBCL that are not dependent on BCL-2, venetoclax was not only ineffective but also appeared to drive tumor growth in our DLBCL PDX model." (PMID 41484790, 2026). "Endpoints encompassed body weight, thigh tumor volume, hematological profiling, histology, immunohistochemistry identification of cleaved caspase 3, and real-time PCR quantification of BAX, BCL-2, and caspase 3 mRNA, utilizing the BAX/BCL-2 ratio as an indicator of apoptotic equilibrium." (PMID 41749157, 2026). "In addition, we observed the local expansion of tumor cells in the paraspinal bone in MM mice and found that the phosphorylation of PI3K, AKT, and mTOR and the expression of BCL-2 were inhibited in the local tumor tissues of both CB and But groups, just as the results presented in vitro." (PMID 41481427, 2026). "BCL-2 activity is directly controlled by AKT/mammalian target of rapamycin (mTOR) signalling, and a combination of crizotinib with mTOR inhibitor Torin2 prolonged survival of mice with ALKF1174L/MYCN NB tumours, which overexpress BCL-2 and are resistant to crizotinib." (PMID 41511287, 2025). "Additionally, similar to migration toward FBS, the co‐culture between the undifferentiated HL‐60 Bcl‐2 cells and tumor cells did not result in an increase in migration toward fMLP further supporting the effects of specifically the differentiated neutrophils." (PMID 39696759, 2025). "The antiapoptotic protein B‐cell lymphoma‐2 (BCL‐2) has been a focus of intensive research efforts, as changes in BCL‐2 expression levels can contribute to improperly regulated apoptotic activity and aberrant cell proliferation conducive to oncogenesis and tumor progression." (PMID 40344485, 2025). "Notably, the tumor also exhibited a double expressor lymphoma (DEL) phenotype, with Bcl-2 expression at 95% and c-Myc expression at 70%, suggesting aggressive biological behavior that may have contributed to the rapid disease progression." (PMID 41229502, 2025). "Studies have shown that tumor-derived exosomal miR-21 and miR-522-3p could participate in gefitinib resistance by regulating PI3K/Akt signaling pathway, while exosomal miR-214 could confer gefitinib resistance via Bax/Bcl2 signaling." (PMID 40444086, 2025).
tumor (continued). "In particular, it has been demonstrated that Bcl-2 overexpression prevents prostate cancer cells from passing through apoptosis, prevents TRAIL-induced apoptosis in neuroblastoma, glioblastoma, and breast cancer cells, and gives tumor cells multidrug resistance." (PMID 40868135, 2025). "However, CD34 is not a specific immunomarker of SFT and it can be negative in about 10% of SFTs, furthermore, CD99 and BCL2 are usually expressed in many other neoplasms." (PMID 40027129, 2025). "Similarly, silencing PTBP1 decreases Bcl-2 and LHFPL3-AS1-long expression and reduces tumour size." (PMID 41463281, 2025). "Consistent with this hypothesis, the patient manifesting with late F‐NHL relapse originated from DLBCL with typical molecular and IHC profile of a GCB neoplasm with BCL2 but not MYC re‐arrangements." (PMID 40838116, 2025). "In addition, detection of the Bax and Bcl-2 proteins in tumor tissues by WB and immunofluorescence revealed that PVT effectively upregulated the proapoptotic protein Bax and downregulated the antiapoptotic protein Bcl-2." (PMID 40076586, 2025). "Furthermore, its pro-apoptotic effects are often cell-type specific, and in some resistant tumor models, betulinic acid fails to induce strong caspase activation due to compensatory anti-apoptotic mechanisms such as upregulation of Bcl-2 or survival." (PMID 40572628, 2025). "Focusing on three clinically relevant targets (tau, BCL-2, and TDP-43), we validated AI-identified candidates and discovered PE859, obatoclax, and B3, which supported applications in spectral analysis, drug screening, pathological labeling, cell imaging, and ex vivo tumor imaging." (PMID 41441857, 2025). "FISH analysis of a DLBCL tumor revealed an atypical MYC rearrangement with gain and amplification (66% of nuclei, including 34% with a 3–5+ fusion signal plus one green signal (3-ampF1G) and 32% with 3-ampF2G), a BCL2 rearrangement (73% of nuclei), and an IGH::BCL2 fusion (76% of nuclei)." (PMID 41010038, 2025). "It has been shown that the upregulated hub MMRG genes BCL2, MAVS, FKBP8, NBR1, and SLC25A6 and their products can participate in regulating drug resistance of tumour cells and the antitumour immune response and may be associated with the activation of inflammatory signalling pathways." (PMID 41463291, 2025). "We analyzed the expression of tumor-related markers, including VEGF (a key pro-angiogenic factor), and apoptotic genes, BAX (pro-apoptotic) and BCL2 (anti-apoptotic), to assess whether dynamic culture within the BAF bioreactor would alter the tumorigenic characteristics of SAOS-2 cells." (PMID 41439917, 2025). "Finally, simultaneous inhibition of Notch and Hh signaling sensitized prostate cancer tumor-initiating cells to docetaxel, a chemotherapy drug, by inhibiting AKT and downregulating the anti-apoptotic protein Bcl-2, highlighting the potential of targeting multiple pathways in CSC-driven cancers." (PMID 40003637, 2025). "Immunohistochemistry demonstrated tumor positivity for vimentin, epithelial membrane antigen (EMA), progesterone receptor (PgR), and thyroid transcription factor-1 (TTF-1) and negativity for cytokeratin and B-cell lymphoma-2 (Bcl-2), with a Ki-67 proliferation index of <1%." (PMID 40265140, 2025). "The histopathologic subtype of DLBCL in this patient is the non-GCB subtype with MYC/BCL-2 dual expression and a high Ki-67 proliferative index, consistent with a biologically proliferative tumour, which is reflected in the clinical presentation of acute splenomegaly with splenic infarcts." (PMID 41306146, 2025). "Furthermore, Bcl2 and Bcl2l2 expression in tumor cells were relatively low and not increased by EGFR-TKI treatment." (PMID 39122703, 2024). "Tumor regression was also observed in vivo in xenograft tumor models (SNU-398 HCC cell-inoculated mice) that were fed an arginine-free diet and treated with a GCN2 inhibitor and senolytic compounds (such as ABT-263, a Bcl-2/Bcl-xl inhibitor) compared to control groups." (PMID 39682684, 2024).
tumor (continued). "In addition to high sequence homology and similar role in regulating apoptosis and response to therapy, Bcl-2 and Bcl-xL also have common non-canonical roles that elicit tumour-promoting effect." (PMID 38755629, 2024). "The tumor cells do not express Bcl-2, CD99, or CD34, which is beneficial for differentiation." (PMID 39206171, 2024). "Furthermore, VCN-AgNPs increased the apoptotic proteins Bax and caspase-3, decreased the anti-apoptotic protein (Bcl-2), increased the inflammatory markers TNF-α and IL-1β, and inhibited angiogenesis by lowering VEGF levels in tumor tissues, all of which led to apoptosis." (PMID 39513869, 2024). "The T16S H2a variant (H2aC1) is overexpressed in oestrogen dependent tumour cells and oestrogen receptor positive, but not negative, cells; the H2aC1 HAR domain is reported to recruit the oestrogen receptor to the promoter regions of BCL2 and c-MYC18,57." (PMID 39604683, 2024). "Furthermore, high molecular weight polysaccharides extracted from Cordyceps sinensis not only enhance the immune function of mice but also induce tumor cell apoptosis through the Cytochrome-c/Caspase8/3 and IL-10/STAT3/Bcl2 pathways, thereby exerting anti-tumor effects." (PMID 38892575, 2024). "However, there was a notable tendency for Bcl-XL in MCF-7 and Bcl-2 in MDA-MB-231 cells to restore their protein levels after 48 h of treatment, which suggests that tumor cells might activate defense mechanisms to counteract the stress induced by DDC." (PMID 38475417, 2024). "Although the main function of Bcl-2 and Bcl-xL proteins is anti-apoptotic, their non-canonical role in different tumor histotypes is now generally recognized, being involved in numerous processes, such as autophagy, angiogenesis, cell migration and invasion, regulation of microRNAs." (PMID 38755629, 2024). "Furthermore, animal studies demonstrated that glabridin intervention significantly slowed tumor tissue growth in mice, resulting in up-regulation of cellular Bax expression and down-regulation of B-cell lymphoma-2 (Bcl-2), HK-2, and LDHA expression in tumor tissues." (PMID 39723390, 2024). "BCL2 expression was found to have a negative correlation with tumor suppressive miRs, such as miR-195, miR-497, and miR-193b, which could potentially explain the outcomes of low expression of BCL2." (PMID 39048974, 2024). "Furthermore, RSL3 inhibited tumor growth and decreased MYB and Bcl-2 expression in vivo." (PMID 38956026, 2024). "It has been widely described that Nrf2 overexpression in different tumor types contributes to pro-oncogenic processes and chemoresistance by promoting the transcription of antioxidant (NQO1), detoxifying (SULT1A1), and anti-apoptotic (BCL-2) enzymes with ARE element." (PMID 39034849, 2024). "Studies on the U-2946 cell line in DLBCL revealed that its unique profile (MCL1 overexpression and lack of BCL-2 expression) results in resistance to BCL-2 inhibitors such as ABT-263, highlighting the need for therapy personalization based on the molecular profile of the tumor." (PMID 39685591, 2024). "Moreover, the SFT tumor cells were positive for CD99 and Bcl-2." (PMID 39206171, 2024). "While the induction of tumor cell apoptosis was massive and rapid in the H4 cell line with no detectable Bcl-2 and a low level of Bcl-xL, it was delayed and much less in extent in A172, U-87 and U-118 cell lines with higher levels of pro-survival Bcl-2 family proteins." (PMID 39190205, 2024). "Finally, BCL2 inhibition had antitumor activity in some, but not all, BCL2-positive PC models, highlighting the need for combination strategies to enhance tumor cell apoptosis and enrich response." (PMID 39286979, 2024). "It was demonstrated that a decrease in the Bax/Bcl2 ratio is a negative prognostic marker and may indicate rapidly progressive tumor growth." (PMID 39063041, 2024).
tumor (continued). "Several of the genes targeted by miR-28 in B cells, including Bcl-2, NF-κB2 and IRAK1, have been shown to be essential for oncogenic signaling in the ABC and GCB genetic subtypes of DLBCL, and our findings are thus in agreement with the anti-tumor effect of miR-28 observed in ABC- and GCB-DLBCL." (PMID 37852959, 2023). "In addition, tumor HE staining and immunohistochemical indices (PCNA, Ki-67, Cleaved-caspase-3, Bcl-2) confirmed that Arte could be a relatively effective sensitizer and enhance 5-FU antitumor activity." (PMID 37498338, 2023). "MiR-497 may regulate proliferation, survival, and tumor vascular permeability of chemoresistant NB cells possibly by targeting genes involved in DNA damage response (WEE1 and CHEK1), cell growth and survival (AKT3 and BCL2), and angiogenesis (VEGFA)." (PMID 36874032, 2023). "Because Mcl-1 is the most overexpressed anti-apoptotic gene in senescent cancer cells, including Bcl-2-negative senescent tumor cells, pharmacologically suppressing Mcl-1 can ultimately eradicate senescent prostate cancer cells, preventing the spread of the tumor and metastases." (PMID 36980256, 2023). "In addition, proteins with dysregulated expression in tumor cells, such as Bcl2, Pim3, PI3K/Akt, etc., could all mediate radiation resistance by affecting DNA damage repair in tumor cells." (PMID 36959858, 2023). "Moreover, the results of Western blotting also demonstrated that knockdown of HK2 could markedly suppress the expression of Bcl-2 and p-ERK and increase the expression of Bax in tumor tissues." (PMID 37854321, 2023). "None of the tumor cells expressed BCL2, CD3, CD5, MUM1, and CyclinD1." (PMID 37539011, 2023). "Mechanistically, butein is known to: (i) regulate BCL2/Bax ratio, induce caspase activity, and consequently drive apoptosis; (ii) stimulate DR5 and mediate caspase-3-dependent apoptosis in TRAIL-resistant cells; and (iii) inhibit NFκB and dictate NFκB-mediated CXCR4-dependent tumor cell migration." (PMID 38249515, 2023). "In vivo studies reveled that apigenin treatment reduced tumor growth and a significant decrease in HDAC activity that correlated with increased levels of p21/waf1and Bax protein along with a reduction in protein levels of bcl2 that favored apoptosis in tumor cells of the mice." (PMID 38596245, 2023). "Furthermore, JQ1-mediated BET inhibition could suppress the transcription of several downstream oncogenes (e.g., BCL-2, C-Myc, and CDK-6) to inhibit tumor growth." (PMID 37328484, 2023). "Mice lacking either PUMA or BIM, two of the BH3-only proteins that can inhibit all pro-survival BCL-2 proteins, do not spontaneously develop tumours, but mice lacking both of these critical initiators of apoptosis develop plasma cell-like tumours with advanced age." (PMID 36342579, 2023). "Indeed, multiple studies assessing administration of these inhibitors, including on the same day, reported that specifically inhibiting MCL-1 and BCL-2 was effective at reducing tumor burden, without overt toxicity concerns." (PMID 37864894, 2023). "Thus, we hypothesized that drugs that activate PP2A could reverse venetoclax resistance via dephosphorylation of BCL-2, MCL-1, BAD, and BAX, thereby resensitizing tumor cells to BCL-2 inhibition." (PMID 37751299, 2023). "Interestingly, we find that the Myeloid Cell Leukemia 1 (Mcl-1) is the most expressed anti-apoptotic gene in senescent tumor cells, being overexpressed even in Bcl-2-negative senescent cancer cells." (PMID 35449130, 2022).
tumor (continued). "Interestingly, and in sharp contrast to KMT2A-r models, BCL-2+BCR::ABL1 mutated samples did not respond to VEN application, with similar blast kinetics and tumor cell frequencies in controls and treated animals." (PMID 35778418, 2022). "The results exhibited that Bcl-2 and ki-67 were increased in primary cells after 4 weeks of chemotherapy, and the expression of cleaved PARP and Bax were decreased, indicating that tumor proliferation was accelerated and apoptosis rate was decreased after 4 weeks of chemotherapy." (PMID 35487914, 2022). "We may postulate that the translocations that lead to high BCL-2 and high MYC expression in DHL may arise at the GC B cell stage but that, as evidenced by the RNA-seq analysis, the high expression of MYC/BCL-2 is what drives the tumour signature." (PMID 35961968, 2022). "We also noticed that the Bax/Bcl-2 ratio was exponentially increased by IOL and slightly increased by ID, suggesting that iron imbalances might have increased cell death and may be involved in reducing tumor severity." (PMID 35631174, 2022). "In addition, co-treatment with EX527 markedly reduced the proportion of cleaved caspase-3 positive cells and Bax expression, but enhanced Bcl2 levels in gAcrp-treated tumors, indicating that inhibition of SIRT-1 prevented tumor cells from apoptosis by adiponectin." (PMID 34986886, 2022). "Here, we describe a population of senescent tumor cells that do not rely on Bcl-2 to survive." (PMID 35449130, 2022). "Interestingly, Bcl-2 expression was reduced in the pure squamous or mixed tumor tissue from WT mice relative to MA, consistent with a lack of requirement for Bcl-2 in the squamous lesions." (PMID 35681213, 2022). "The Bax/BCL2 ratio in the control group of B16F10 and LMM were both approximately 1.3, but the percentage in both cell lines increased over 1.5 when the 125 μg/mL CM was adopted; thus, CM could induce apoptosis in tumor cells." (PMID 36009221, 2022). "Additionally, they regulated the expression of apoptotic genes (Caspase 3, Bax, Bcl2, iNOS, SOD) in the tumor, although the nanoliposome-encapsulated PRF were revealed to be of higher potential, compared to nonencapsulated PRF, in improving the health parameters." (PMID 36552412, 2022). "Finally, the growth of large, solid tumor microtissues on RGD-free HAGM cryogels, along with HA-mediated CD44 activation, is probably responsible for the overexpression of genetic markers for hypoxia and tumor aggressiveness, including HIF1α, WNT-11, BCL2, CD73, and VEGF." (PMID 35198956, 2022). "The tumor immunohistochemistry results were B‐cell lymphoma 2 (BCL‐2) positive, focal CD34 +, focal cytoplasmic CD99+, epithelial membrane antigen (EMA) and Panker negative, actin negative, S100 protein‐negative, Papanicolaou and Block cell with a positive result for malignant tumor cells." (PMID 35414906, 2022). "Moreover, vandetanib treatment could decrease the protein expression of MCL‐1 and BCL‐2 and increase the expression of BAD, BAX and BAK in K562 tumor tissues, which was consistent with the regulation of apoptosis‐related proteins in cancer cells in vitro." (PMID 35689424, 2022).